LSM4 (LSM4 homolog, U6 small nuclear RNA and mRNA degradation associated)
Description:
Plays a role in pre-mRNA splicing as component of the U4/U6-U5 tri-snRNP complex that is involved in spliceosome assembly, and as component of the precatalytic spliceosome (spliceosome B complex). The heptameric LSM2-8 complex binds specifically to the 3'-terminal U-tract of U6 snRNA.
Synonyms: GRP; YER112W
Tractability: Small molecule: a structure with a bound ligand is known. PROTAC: UniProt records ubiquitination sites on it; ubiquitination databases record sites on it; its protein half-life has been measured.
Gene: Protein-coding gene on chromosome 19 (18,306,231 to 18,323,112, reverse strand). Ensembl gene ENSG00000130520.
Subcellular location: Nucleus
Subcellular location (Human Protein Atlas): Vesicles
Pathways (Reactome):
Metabolism of RNA: mRNA Splicing - Major Pathway; mRNA decay by 5' to 3' exoribonuclease
Gene Ontology:
Molecular function: PH domain binding; protein binding; RNA binding; U6 snRNA binding
Biological process: mRNA splicing, via spliceosome; deadenylation-dependent decapping of nuclear-transcribed mRNA; P-body assembly; RNA splicing; spliceosomal snRNP assembly; spliceosomal tri-snRNP complex assembly; nuclear-transcribed mRNA catabolic process; RNA processing
Cellular component: cytoplasm; cytosol; Lsm2-8 complex; membrane; nucleus; precatalytic spliceosome; protein-containing complex; spliceosomal complex; U2-type precatalytic spliceosome; U4/U6 x U5 tri-snRNP complex; nucleoplasm; P-body; spliceosomal tri-snRNP complex; U4/U6 snRNP; U4atac/U6atac snRNP; U4atac/U6atac x U5 tri-snRNP complex; U6 snRNP; U6atac snRNP
Genetic constraint (gnomAD): Loss-of-function variants: 15 observed, 22.5 expected, observed/expected ratio (o/e) 0.67, 90% interval 0.44 to 1.03. The upper end of that interval is the gene's LOEUF score, 1.03, which puts it in group 4 of 6, group 1 being the genes least tolerant of losing a copy. Missense variants: 127 observed, 185.8 expected, observed/expected ratio (o/e) 0.68, 90% interval 0.59 to 0.79. Synonymous variants: 90 observed, 76.02 expected, observed/expected ratio (o/e) 1.18, 90% interval 1 to 1.41.
Homologues: Orthologues: macaque LSM4 (100% identical), pig LSM4 (100% identical), dog LSM4 (99% identical), guinea pig LSM4 (98% identical), mouse Lsm4 (96% identical), chimpanzee LSM4 (88% identical), zebrafish lsm4 (85% identical), rat Lsm4 (80% identical), tropical clawed frog lsm4 (78% identical), Drosophila melanogaster CG17768 (65% identical), Caenorhabditis elegans lsm-4 (57% identical). Paralogues in human: SNRPD3 (29% identical), SNRPD1 (25% identical).
Diseases named in the same sentence as LSM4 in open-access papers:
LSM4 is named in the same sentence as 32 diseases in open-access papers, as found by Europe PMC text mining. Sharing a sentence is not in itself a finding about the gene and the disease. The quoted sentences say what the papers report.
hepatocellular carcinoma (6 papers, 2021 to 2025). A malignant tumor that arises from hepatocytes. "LSM4 has been implicated in the progression of pancreatic cancer, breast cancer and hepatocellular carcinoma." (PMID 40432923, 2025). "LSM4 is highly expressed in hepatocellular carcinoma tissues, and knockdown of LSM4 reduces the cell proliferation and migration of hepatocellular carcinoma cells." (PMID 40425760, 2025). "In addition, LSM4 overexpression was significantly correlated with poor survival in BC, pancreatic ductal adenocarcinoma (PDAC), and hepatocellular carcinoma (HCC)." (PMID 36371223, 2022).
breast carcinoma (4 papers, 2021 to 2025). "We revealed that LSM4 had higher expression levels in breast tumor and breast cancer sub-types than in normal samples, and was associated with poor survival outcomes." (PMID 34638387, 2021). "Interestingly, Joseph S. Baxter et al32 have also identified that LSM4 is one of 110 target genes at 33 breast cancer risk loci based on Capture Hi-C technology, which supports the conclusions of the present study." (PMID 34341433, 2021). "Based on the TCGA_BRCA and match TCGA normal and GTEx data of GEPIA database, the mRNA expression levels of these genes (CENPL, ISG20L2, MRPL3 and LSM4) were also significantly higher in breast cancer tissues than normal tissues." (PMID 34341433, 2021). "A total of 18 methylated CpG sites of LSM4 were found using the MethSurv database, with nearly half of the CpG sites having predictive relevance in breast cancer patients." (PMID 34638387, 2021). "The expression levels of each hub gene (CENPL, ISG20L2, MRPL3, and LSM4) was correlated with EZH2 in three different breast cancer cell lines (p < 0.01)." (PMID 34341433, 2021). "DiseaseMeth version 2.0 analysis displayed that the mean methylation levels of CENPL, MRPL3 and LSM4 were all significantly reduced in breast cancer compared to normal breast tissues (P < 0.05)." (PMID 34341433, 2021). "As an oncogene, growing evidence has identified EZH2 was closely related to breast cancer development and progression through multiple molecular mechanisms, but no studies are related to the roles of CENPL, ISG20L2, MRPL3 and LSM4 in breast cancer." (PMID 34341433, 2021). "To further elucidate the lurking biological functions of CENPL, ISG20L2, MRPL3 and LSM4 in breast cancer occurrence and development, we conducted GSEA and GSVA using METABRIC dataset." (PMID 34341433, 2021). "In DiseaseMeth 2.0 database, the correlation analysis of DNA methylation patterns of hub genes with mRNA expression revealed that CENPL, MRPL3 and LSM4 were hypomethylated in breast cancer samples compared with adjacent normal ones, while ISG20L2 was hypermethylated in breast cancer sample." (PMID 34341433, 2021). "Additionally, genetic alterations of CENPL, ISG20L2, MRPL3, and LSM4 were further examined in cBioPortal database, showing these four hub genes were altered in 570 (26%) of 2173 breast cancer patients." (PMID 34341433, 2021). "Generally speaking, the DNA methylation patterns negatively correlates with mRNA expression, which is consistent with the observed up-regulation of CENPL, MRPL3 and LSM4 in breast cancer, while the latest research suggested DNA hypermethylation can lead to mRNA upregulation." (PMID 34341433, 2021). "Interestingly, we observed that LSM4 was closely ranked with other breast cancer biomarkers, such as DPP3, CDK5, and TRIB3." (PMID 34638387, 2021). "Considering the five hub genes, which were identified based on PPI networks and WGCNA, share the same signaling pathways during breast cancer progression, we conducted correlation analysis between the four novel hub genes (CENPL, ISG20L2, LSM4 and MRPL3) and EZH2." (PMID 34341433, 2021). "Compared to normal mammary epithelial cell (MCF10A), the RCPs of each hub gene in both breast cancer cell lines (MCF7 and MDA-MB-231) showed a significant increase (p < 0.05), but the RCPs of ISG20L2 were reduced and the LSM4 were similar as observed in SKBR3 cell." (PMID 34341433, 2021). "Meanwhile, LSM4 was also correlated with “Immune response IL-15 signaling via MAPK and PI3K cascade”, “Cell cycle spindle assembly and chromosome separation”, and “Mitogenic action of ErbB2 in breast cancer”, which are immune- and cell cycle-related pathways that play roles in BRCA growth." (PMID 34638387, 2021). "Among these, many studies on EZH2 in breast cancer have been reported, but no studies are related to the roles of CENPL, ISG20L2, MRPL3 and LSM4 in breast cancer." (PMID 34341433, 2021).
ovarian carcinoma (4 papers, 2021 to 2023). A malignant neoplasm originating from the surface ovarian epithelium. "Mechanically, circ_0025033 influenced the expression of LSM4 via sponging miR-184 in ovarian cancer cells." (PMID 38152652, 2023). "Overexpression of LSM4 abolished the circ_0025033 knockdown-mediated inhibitory functions on cell invasion, colony formation, migration and glycolysis metabolism in ovarian cancer." (PMID 38152652, 2023). "In addition, Hou and Zhang report that circ_0025033 downregulation suppressed colony formation ability, mobility, and glycolysis metabolism in ovarian cancer cells via regulation of the LSM4/miR-184 axis." (PMID 36273140, 2022). "Interfered with circ_0025033 or LSM4 expression could inhibit colony formation, migration, invasion and glycolytic metabolism of ovarian cancer cells." (PMID 34394080, 2021).
liver cancer (3 papers, 2021 to 2025). An epithelial or non-epithelial malignant neoplasm that arises from the liver. "While prior studies have implicated SNRPA1 and LSM4 in RNA splicing and cancer, and TMED10 in autophagy and vesicle trafficking in melanoma and liver cancer, their involvement in OC has been explored systematically by a limited number of studies." (PMID 40826138, 2025). "This contrasts with prior reports linking SNRPA1 and LSM4 expression to poor prognosis in colorectal and liver cancers, highlighting possible tissue-specific roles or the influence of other clinical and molecular confounders in OC." (PMID 40826138, 2025). "Similarly, the expression levels of LSM4 (p = 0.072) and RNASEH2A (p = 0.036) were also elevated in liver cancer organoids." (PMID 40432923, 2025).
pancreatic cancer (3 papers, 2021 to 2025). "LSM4 is involved in the disease progression of pancreatic cancer by mediating the formation of U4/U6 snRNP." (PMID 36389112, 2022). "LSM4 has known as a member of the LSM family of RNA-binding proteins, plays an important role in pre-mRNA splicing by mediating U4/U6 snRNP formation, and involved in pancreatic cancer." (PMID 34638387, 2021).
esophageal cancer (2 papers, 2021 to 2022). A primary or metastatic malignant neoplasm involving the esophagus. "LSM4 has been found to affect the production and movement of tumor cells in esophageal cancer." (PMID 36389112, 2022).
lung carcinoma (2 papers, 2021 to 2022). "At present, the mechanism of action of LSM4 and LSM5 in lung cancer has not been reported." (PMID 36389112, 2022).
lymph node metastasis (2 papers, 2021). "LSM4 was associated with clinical stage, tumor grade, and lymph node metastasis status (p < 0.05)." (PMID 35096017, 2021). "After analyzing the expression of LSM4 based on lymph node metastasis status and tumor grade, the same upward trend was also observed in our study." (PMID 35096017, 2021). "In this study, our data not only showed the expression level of CENPL, ISG20L2, LSM4 and MRPL3 were strongly associated with age, lymph node metastasis and higher SBR grade, but also significantly upregulated in triple negative breast cancer patients compared to non-triple negative breast cancer." (PMID 34341433, 2021).
breast tumors (1 paper, 2021). "Of interest, our findings through DNA methylation level analysis by using UALCAN database also support the consistent trend, which show LSM2, LSM4, LSM10 were upregulated in primary breast tumors, while LSM6 methylation levels were downregulated." (PMID 34638387, 2021). "Methylation levels of LSM2, LSM4, and LSM10 were upregulated in primary breast tumors, while LSM6 methylation levels were downregulated." (PMID 34638387, 2021).
colorectal cancer (1 paper, 2021). A primary or metastatic malignant neoplasm that affects the colon or rectum. "Among several signaling pathways, LSM4 was significantly correlated with “Beta catenin-dependent transcription regulation in colorectal cancer”, consistent with a previous study." (PMID 34638387, 2021).
cutaneous melanoma (1 paper, 2022). A primary melanoma arising from atypical melanocytes in the skin. "The protein expression of LSM2, LSM4, and LSM12 was upregulated in cutaneous melanoma." (PMID 36371223, 2022).
neuroblastoma (1 paper, 2024). Neuroblastoma (NB) is the most common solid, extracranial childhood tumor. "We found that SNRPD3, SNRPF and LSM4 had the strongest independent prognostic effect on neuroblastoma patient outcome among the core spliceosome assembly genes as measured by hazard ratios for event-free (EFS) and overall (OS) patient survival." (PMID 38049564, 2024).
ovarian tumors (1 paper, 2025). "They reported that LSM4 was upregulated in ovarian tumors and exhibited dynamic expression across epithelial, endothelial, and stromal cell types, including fibroblasts, during differentiation processes." (PMID 40826138, 2025).
Stroke (1 paper, 2023). Sudden impairment of blood flow to a part of the brain due to occlusion or rupture of an artery to the brain. "Strikingly, LSM4 methylation has been implicated in the formation of large arterial plaques, which is a known risk factor for stroke." (PMID 37891634, 2023). "Our research findings highlight the significance of genes associated with the UPR pathway, including ATF6, EXOSC5, EEF2, LSM4, NOLC1, BANF1, and DNAJC3, in the occurrence of stroke." (PMID 37891634, 2023).
cancer (9 papers, 2019 to 2025). A tumor composed of atypical neoplastic, often pleomorphic cells that invade other tissues. "From the results of a TME analysis, CD8+ T cells, macrophages, neutrophils, and DCs were strongly associated with LSM4 in targeting cancer cells, leading to a potential role of LSM4 in immunotherapy." (PMID 34638387, 2021). "In addition, LSM4 overexpression has been associated with rapid cancer progression in BC." (PMID 36371223, 2022). "LSM4 has also been found to be upregulated in several types of cancer, such as breast cancer, and in early-stage pancreatic ductal adenocarcinoma, where it is associated with a poor prognosis." (PMID 37762007, 2023). "As LSM4 is also involved in some cancers, it will be interesting to use the simple yeast model to find LSM4 targets for the development of antitumoral molecules." (PMID 37762007, 2023). "We explored the expression of LSM4 based on cancer stage and found that LSM4 expression was higher in advanced clinical stages." (PMID 35096017, 2021). "In order to determine the cancer-related signaling pathways related to LSM4, GSEA analysis was performed using the LSM4 expression data contained in the TCGA dataset." (PMID 35096017, 2021). "In summary, our study shows that LSM4 expression is related to cancer stage, tumor grade, and lymph node metastasis status." (PMID 35096017, 2021). "We investigated mutations of LSM genes in BRCA patients from TCGA Pan-Cancer Atlas (n = 1082 patients) in the cBioPortal platform, and found surprisingly high rates of alterations in LSM1 (25%), LSM2 (11%) LSM4 (8%), and LSM14B (23%)." (PMID 34638387, 2021). "In addition, we analyzed the associations between LSMs (LSM2 and LSM4) and the expression of immunoinhibitors, immunostimulators, and MHC molecules in various types of human cancers." (PMID 36371223, 2022). "Therefore, LSM4 is not only associated with BRCA, but is also involved in various other types of cancer." (PMID 34638387, 2021). "Summarily, the current evidence indicated that LSM4 might act as a cancer-promoting factor and participate in the occurrence and malignant progression of HCC, and it has the potential as the diagnostic biomarker of HCC and the predictor of poor prognosis." (PMID 35096017, 2021). "The list of genes, with known human homologs not already associated with cancer phenotypes, are prime candidates as novel cancer susceptibility genes for future studies (as an example see discussion of LSM4 below)." (PMID 31270132, 2019). "Pan-cancer analysis using TCGA tumor samples revealed a significant positive correlation between TRA16 and LSM4 (R = 0.63), as well as TRA16 and RNASEH2A (R = 0.6)." (PMID 40432923, 2025). "Expression of TBCA, COMMD7, LSM4, and FKBP1A were significantly lower in the cancer tissues than the normal tissues." (PMID 39012280, 2024). "Furthermore, when exploring correlations between immune cells and cancer cells in the TME, we discovered that not only was LSM4 expressed by cancer cells, but most immune cells in several immune deconvolution methods also infiltrated BRCA tumors and subtypes with high expression of LSM4." (PMID 34638387, 2021).
tumor (9 papers, 2018 to 2025). "Interestingly, we found that high LSM4 expression was associated with myeloid-derived suppressor cells (MDSCs), which were suggested to constitute a tumor-favoring microenvironment in basal, and luminal A and B subtypes." (PMID 34638387, 2021). "Functional validation revealed that knockdown of either circ_0025033 or LSM4 significantly inhibited colony formation, migration/invasion, and glycolysis in OC cell lines, implicating LSM4 as a key driver of tumor growth and metabolic reprogramming." (PMID 40826138, 2025). "In this study, Tcm infiltration was positively correlated with LSM8 and LSM12 but negatively correlated with LSM2 and LSM4, which was consistent with the effect of genes on tumor prognosis." (PMID 36371223, 2022). "Our method provides an observation of correlations between LSM4 expression and BRCA tumor, and revealed that LSM4 overexpression was associated with progressive stages of BRCA." (PMID 34638387, 2021). "LSM2 and LSM4 proteins were overexpressed in tumor tissues with similar patterns in BRCA patient samples in the HPA dataset." (PMID 34638387, 2021). "LSM4 expression exhibited positive correlations with tumor purity (r = 0.209, p = 2.56 × 10−11), CD8+ T cells (r = −0.325, p = 1.78 × 10−25), macrophages (r = −0.309, p = 2.9 × 10−23), neutrophils (r = −0.161, p = 5.75 × 10−7), and DCs (r = −0.12, p = 2.17 × 10−4)." (PMID 34638387, 2021). "Moreover, a heatmap was conducted to clearly describe the relationship of LSM4 expression levels between two different phenotypes: normal and tumor tissues." (PMID 34638387, 2021). "We hypothesized that the LSM family, especially LSM4, might possess a novel role in tumor growth, and infiltration of immune cells may provide better predictions of survival rates in BRCA patients." (PMID 34638387, 2021). "We found that LSM4 was also overexpressed in tumor samples, and underexpressed in normal controls." (PMID 34638387, 2021). "For example, the expression of LSM4 in BRCA was significantly increased and was closely related to lymph node metastasis and tumor cell proliferation." (PMID 35096017, 2021). "31B was significantly lower expressed while LSM4 and ILF2 were significantly higher expressed in tumor versus matched normal mammary gland tissue." (PMID 30940821, 2019).
bacterial infection (3 papers, 2024 to 2025). "Bacterial infection reduces LSM4 methylation levels, enhancing plant resistance, a mechanism related to reduced intron retention of immune-related genes." (PMID 40395926, 2025). "However, during bacterial infection, LSM4 methylation declined and plants harbouring unmethylated LSM4 showed better protection against Pseudomonas but were hypersensitive to ABA and salt stress in comparison to those expressing the wild-type LSM4." (PMID 41175264, 2025). "Specifically, bacterial infection leads to a decrease in PRMT5 expression, accompanied by reduced arginine methylation of key proteins such as AGO2 and LSM4." (PMID 40395926, 2025).
infection (2 papers, 2021 to 2025). The state of being infected such as from the introduction of a foreign agent such as serum, vaccine, antigenic substance or organism. "Pathogen infection triggers a decrease in PRMT5 protein levels, which in turn reduces the methylation modification of the spliceosome component LSM4, enhancing resistance by optimizing the alternative splicing of immune-related genes." (PMID 40395926, 2025).
LSM4 also shares sentences with these, for which no sentence is quoted: triple-negative breast carcinoma (2 papers); adenoid cystic carcinoma (1); Alzheimer disease (1); amyotrophic lateral sclerosis (1); colon cancer (1); Huntington disease (1); lung adenocarcinoma (1); Lynch syndrome (1); medulloblastoma (1); melanoma (1); multiple myelomas (1); Parkinson disease (1); stomach adenocarcinoma (1); uterine corpus endometrial carcinoma (1).